TLR4 (toll like receptor 4)
Diseases named in the same sentence as TLR4 in open-access papers (continued):
Sharing a sentence is not in itself a finding about the gene and the disease.
tumor (continued). "Finally, dysfunction of the TLR4 signaling pathway, which thereafter leads to reduced pro-inflammatory cytokines secretion, could contribute to a better tumor prognosis, as observed in patients with HPV-related oropharyngeal SCC." (PMID 39451550, 2024). "Additionally, glycyrrhizin could modulate the HMGB1/RAGE and HMGB1/TLR4 signaling pathways in melanoma, disrupting tumor metastasis, and growth." (PMID 37897664, 2024). "Suggested the mechanisms included enhanced tumor cell metabolism, proliferation and metastasis, induced inflammation and suppressed the host immunity, activated autophagy to confer resistance to chemotherapy and reduced the efficiency of chemotherapy via the Toll-like receptor 4 (TLR4) pathway." (PMID 39334474, 2024). "In contrast, macrophages TLR4 wild-type adoptive transferred in TLR4-deficient mice bearing tumor, showed a significantly higher NF-κB activity, enhanced release of inflammatory factors such as TNF-α and VEGF, thus prompting an increased NF-κB activity in tumor cells and tumor growth in vivo." (PMID 38397187, 2024). "Similarly, the tumor microenvironment Toll-like receptor 4 (TLR4) exhibited this trend." (PMID 38544837, 2024). "When LPS, a component of gram-negative bacteria, enters the bloodstream, it can activate an inflammatory cascade by binding to TLR4 on immune cells, stimulating the release of proinflammatory cytokines and chemokines, which may act systemically upon the tumour microenvironment." (PMID 39340753, 2024). "Thus, in peritonsillar tissues with the TLR4 cascade upregulated, both the innate and adaptive immune systems are activated, enhancing inflammation, supplying the primary site with tumor-specific immune cells from the peritumoral tonsillar tissue, and finally suppressing OPC lymph node metastasis." (PMID 38416737, 2024). "However, chronic activation of TLR4 signaling can also lead to the recruitment of immunosuppressive cells, such as Tregs and myeloid-derived suppressor cells (MDSCs), which can inhibit the immune response, promoting tumor growth." (PMID 37345131, 2023). "However, our analysis did show that non-tumor comparative tissue had the highest TLR4 expression." (PMID 35841426, 2023). "Notably, Fn-EVs-enhanced tumor growth and liver metastasis were rescued by TLR4 silence." (PMID 37221488, 2023). "In turn, released NE, among other factors, might spread through biofluids (for instance, peritoneal fluid) to reach TLR4 on tumor cells and activate intracellular signals that increase the release of pro-metastatic cytokines, forming a positive pro-metastatic feedback loop." (PMID 36983067, 2023). "Thus, targeting TLR4 could have several potential therapeutic effects, such as the induction of tumor cell death." (PMID 37896221, 2023). "Importantly, in vitro and in vivo studies collectively confirmed that F. nucleatum-derived EVs contribute to tumor growth and liver metastasis in BC through a TLR4-dependent mechanism since the knocking down of TLR4 in BC cells effectively counteracted the effect of F. nucleatum-derived EVs." (PMID 37221488, 2023). "Indeed, OAd-MSC TLR4−/− induced high proinflammatory response in the tumor microenvironment." (PMID 36875156, 2023). "However, PepO-primed TLR4−/− M2 BMDM effectively inhibited tumor growth." (PMID 37925462, 2023). "Consistent with our speculation, there is extensive and complex intercellular communication between tumor cells and all HSPA1 positive cell clusters, suggesting that TME cells in HCC may be metabolically reprogrammed by tumor cells via the HSPA1-GRIN2D/TLR4 axis to promote tumor progression." (PMID 37914817, 2023). "Furthermore, we found that DOKD inhibited CT26+ tumor cell growth by regulating inflammation, metastasis, and angiogenesis by activating the IL-17/TLR4/NF-κB p65 pathway and inhibiting the activation of the Src/HIF-1α/Erk1/2/Snail/N-cadherin/Vimentin/MMP9 and Erk1/2/HIF-1α/STAT3/VEGFA pathways." (PMID 37239383, 2023).
tumor (continued). "In colorectal cancer, tumor-induced downregulation of monoacylglycerol lipase (MAGL) in TAMs is associated with the accumulation of tri-, di-, and mono-glycerides along with arachidonoylglycerol, enhancing CB2 receptor activity to antagonize TLR4 signaling and mediate immunosuppression." (PMID 37251409, 2023). "Moreover, R. Domenis reported that intratumoral bacteria are likely to activate TLR4 by secreting exosomes to influence tumor progression, which means that cancer cells can mobilize tumor metastasis through paracrine exosomal signaling rather than direct invasion of bacteria." (PMID 37148441, 2023). "Tumor cells and platelets are able to produce microthrombi in the circulation by the binding of the platelet P-selectin to the ligands of tumor P-selectin and thanks to the interaction between platelet TLR4 and the released High Mobility Group Box 1 (HMGB1) protein from the tumor." (PMID 36901997, 2023). "Similarly, in immunomodulatory regimens and platinum-based anti-cancer therapies, bacteria-associated TLR4 agonists were shown to modulate tumor necrosis factor (TNF)- and reactive oxygen species (ROS)-mediated anti-tumor effects of tumor-infiltrating myeloid-derived suppressor cells (MDSCs)." (PMID 36828830, 2023). "Moreover, APOH can bind to lipopolysaccharide and activate NF-KB through TLR4 pathway, thus affecting the metastasis and invasion of tumor cells, which may be one of the potential mechanism of its involvement in tumor metastasis." (PMID 37770976, 2023). "Moreover, previous study suggested that TLR4 could facilitate tumor cells invasion and migration as a cancer stem cell marker in HCC." (PMID 37251918, 2023). "Moreover, a previous study suggested that TLR4 could facilitate tumor cell invasion and migration as a cancer stem cell marker in HCC." (PMID 37251918, 2023). "Furthermore, in vivo study verified the contributive role of Fn-EVs in tumor growth and metastasis of BC, which might rely on its regulation of TLR4." (PMID 37221488, 2023). "Furthermore, Escherichiacoli colonization of the colon contributes to M2 macrophage polarization through TLR-4, which could promote tumor metastasis in CRC." (PMID 35892821, 2022). "Moreover, it has been demonstrated that the activation of Toll-like receptor 4 in tumor cells supports tumor progression by stimulating the release of immunosuppressive exosomes, which allow tumor cells to escape immune surveillance and even play a role in the metastatic process." (PMID 36466871, 2022). "Finally, CXCR4 signaling, where TNC induces CXCL12 in tumor cells (through TLR4), but also binds to CXCL12 (again in the TN3–TN5 domains) thus trapping CD8T cells in the stroma, exerting a Janus function (i.e. both activation and inhibition) on yet another pathway." (PMID 36102918, 2022). "Our data are in alignment with these findings and suggest that increased tumor expression of TLR4 in STS may therefore represent a mechanism for driving immune cell infiltration, especially cytotoxic lymphocytes, and therapies to target this pathway may prove promising." (PMID 35874727, 2022). "Notably, HMGB1 may also favor endothelial progenitor cell homing and increase their neovascularization capacity in a RAGE/TLR4-dependent manner, thus promoting tumor angiogenesis." (PMID 35727208, 2022). "TDEs also engage with other TLRs such as TLR4 and TLR7 on other phagocytes including monocytes and neutrophils in which miRNA, noncoding RNA, and high-mobility group box 1 (HMGB1) transferred by TDEs are implicated in driving the pro-tumor phenotype of these myeloid cells." (PMID 36031601, 2022). "Research has shown that tumours activated the suppression of T-cell and natural killer cell activity, but when TLR4 was inhibited, this tumour-mediated suppression of T-cell and natural killer cells was prevented, which delayed tumour growth and increased survival of the tumour-bearing mice." (PMID 35962138, 2022).
tumor (continued). "The current study highlights that LPS‐induced tumor regression, in part, occurs via regulation of tumor suppressor SMAR1 protein, which eventually dictates the macrophage polarization by reprogramming tumor‐associated macrophages (TAMs) to M1 phenotype via TLR4‐TRIF‐dependent pathway." (PMID 34689394, 2022). "Interestingly, TLR4 has both tumor-promoting and tumor-suppressive effects, and targeting TLR4 activation or inhibition may be a potential therapeutic strategy for different types of tumors." (PMID 35963853, 2022). "Our results provide first evidence that the expression of TLR4 and pSTAT3 on circulating tumor cells (CTCs) and immune cells of BC patients might play a role in peripheral anti-tumor response and metastatic progression, and could be associated with patient outcomes." (PMID 35205801, 2022). "Therefore, TAK-242 mediated alterations of the microbial composition and increased butyrate levels might modulate Tlr4 expression and tumor development." (PMID 34025672, 2021). "Moreover, LPS could activate TLR4 signaling in tumor cells and help tumor cells to escape attack from cytotoxic lymphocyte (CTL) and natural killer (NK) cells." (PMID 34604233, 2021). "Therefore, RAP99-LPS enhances anti-tumor responses in vivo via TLR4." (PMID 34113349, 2021). "Since TLR4-mediated signalling has been reported to be responsible for cell survival, cancer progression, invasion, and metastasis, we next developed phenotypic assays in order to better understand the complex interplay of tumour progression and the TLR4 signalling pathway." (PMID 34502140, 2021). "Here we found a new mechanism that intestinal leakage increased systemic circulation LPS and it further induced intra-tumoral lymphocyte infiltration and as well as upregulated PD-L1 expression via TLR4 signaling pathway, which could promote tumor immune escape." (PMID 34718325, 2021). "Recently, it could be shown in a murine model that the activation of TLR4 resulted in a higher adhesion of tumor cells to the extracellular matrix and increased invasion modulated by NF-κB and ß-integrins, which in turn could imply a higher potential for distant metastasis formation." (PMID 34476575, 2021). "We have also investigated whether TLR4 would affect the tumor-infiltrating immune cells." (PMID 34385421, 2021). "After demonstrating that light-induced activation of TLR4 signalling pathway promotes cell adhesion and the expression of proteins involved in tumour promotion and metastasis, we next examined whether TLR4 activation via light exposure also promotes tumour cell invasion through ECM." (PMID 34502140, 2021). "This could be in terms of induction into the tumour cells, or specifically binding with TLR-4." (PMID 34473709, 2021). "In addition to FadA mechanisms, TLR4 activation by F. nucleatum’ LPS can plausible lead to the activation of Myd88 and NF-κB, which leads to oncogenic overexpression of miR21, resulting in dysregulated growth and infiltration of tumour tissue." (PMID 34949212, 2021). "Therefore, TLR4 activation in DCs and tumor cells exhibits a good anti-tumor immune response." (PMID 34660305, 2021). "In addition, the expression of TLR4 gene is correlated with the tumor stages of KIRC and UCEC." (PMID 34631699, 2021). "However, given its anti-apoptotic activity, overexpression of TLR4 during colonic inflammation could be speculated to protect malignant cells against apoptosis and further promote tumor cell growth." (PMID 34479599, 2021). "However, the issue of whether TLR4 mediates some of the effects of opioids on tumour growth and metastasis is entirely unknown." (PMID 34771442, 2021). "However, tumor-intrinsic TLR4 is negatively correlated with survival." (PMID 34718325, 2021). "Therefore, the ICA may be an effective drug to attenuate the TLR4/MyD88/NF-κB and Wnt/β-catenin signaling pathways to suppress tumor cell proliferation in xenograft in mice models." (PMID 33849528, 2021).
tumor (continued). "CircGFRA1 knockdown can inhibit the resistance of TNBC cells to PTX by reducing the expression of TLR4, which has been found to be activated by paclitaxel to improve tumor cell survival and blocking TLR4 could significantly improve response to paclitaxel therapy in BC." (PMID 33676555, 2021). "Notably, cluster 1 had a stronger immunosuppressive tumor microenvironment (TME) and a higher mutation frequency than cluster 2, especially the mutant genes, such as Kelch-like ECH-associated protein 1 (KEAP1) and toll like receptor 4 (TLR4)." (PMID 32445554, 2020). "Thus, TLR4 is involved in the regulation of anti-tumor immunity in the tumor-bearing host." (PMID 32194422, 2020). "The present studies were done to determine whether Toll‐like receptor‐4 (TLR4), which has been previously shown to be a receptor for fetuin‐A and is commonly expressed in immune cells, could take part in the rapid uptake (< 3 min) of fetuin‐A by tumor cells." (PMID 33073533, 2020). "Thus, the low surface expression of TLR4 on the surfaces of tumor cells growing in culture plates could be due to fetuin‐A which is present in most growth media supplemented with 10% fetal bovine serum." (PMID 33073533, 2020). "Furthermore, activation of TLR4 signaling on M2-polarized TAMs stimulates IL-10 release, thus promoting cancer progression, especially in the advanced stages of metastatic growth of the tumor." (PMID 32283687, 2020). "TLR4 signaling plays a prominent role in the development of both the acute and chronic damaging effects resulting from the pro-inflammatory activity of immunocytes and tumor cells under stress conditions such as bacterial infection and anticancer radiation and chemotherapy." (PMID 32027657, 2020). "Indeed, various studies describe tumor EVs as capable of impacting myeloid cell function whereas PC-EVs were shown to regulate the expression of TLR4 in dendritic cells in vitro." (PMID 33330473, 2020). "Moreover, tumor-secreted cathepsin K (CTSK) could stimulate TLR4 to switch to M2 polarization relying on the mTOR signaling activation." (PMID 33505964, 2020). "As TLR4 pathway is also activated in MM mesenchymal stromal cells (MSCs) driving their commitment toward a pro-inflammatory and pro-tumor behavior, TLR4 inhibition could be an adjuvant therapy to interrupt the self-reinforcing stromal changes in MM microenvironment." (PMID 33409153, 2020). "After the addition of TLR4 inhibitor TAK242 in LPS-induced cell model, the cytokine level decrease, indicates that the aerial part of TDG may compete with TLR4 in interacting with TLR4 to regulate the production of cytokines, thereby regulating immune function and achieving anti-tumor activity." (PMID 33101019, 2020). "Furthermore, RPS3 is confirmed to be safe when using as an adjuvant in tumor-specific antigen DC-based vaccines via TLR4 since RPS3 is nucleoprotein that could induce humoral immunity, producing autoantibodies against itself." (PMID 30819254, 2019). "The microbial lipopolysaccharide (LPS) release induced by irradiation activated innate immune response by TLR4 pathway stimulation and then boosted anti-tumor CD8+ T cells, while antibiotic treatment or LPS neutralization (with polymyxin B) were associated with a decrease of anti-tumor response." (PMID 31533218, 2019). "Increasing experimental evidence has demonstrated that chronic infection and inflammatory processes may lead to tumor genesis, and the tumor genesis was mediated in part through recognition of stimuli by TLR4, therefore, proper expression of TLR4 was very important to the immune system." (PMID 30979040, 2019). "The ΔppGpp S. typhimurium lipopolysaccharide (LPS) promoted mononuclear/macrophage and dendritic cells to secrete IL-1β through the TLR4 signaling pathway, exerting anti-cancer effects, but tumor recurrence occurred in late treatment stages, which might be related to reduced IL-1β levels." (PMID 31754923, 2019).
tumor (continued). "In conclusion, reactive aldehydes, formed as a consequence of an intense oxidative burst of granulocytes, might mediate antitumor effects of granulocytes by impairing tumor cell redox homeostasis and, also, at least in the case of acrolein, induce granulocyte TLR4 expression." (PMID 30934946, 2019). "Interestingly, TLR4/NF-κB signaling mediates diverse tumor growth." (PMID 29788922, 2018). "Given the extensive tumor-promoting functions reported for both IL-6 and IL-8, dysfunction of the TLR4 signaling pathway which thereafter leads to reduced secretion of IL-6 and IL-8, could contribute to a better tumor prognosis, as seen in patients with HPV+ OPSCC." (PMID 29416610, 2018). "Activation of the innate immune system, particularly through TLR-4, may stimulate tumor growth." (PMID 30680070, 2018). "However, studies also shown that TLR4 displayed anti-tumor activity in skin cancer." (PMID 30213077, 2018). "Particularly, TLR4 and its adaptor, myeloid differentiation primary response gene 88 (MyD88), were found to be essential for optimal antigen processing by inhibiting the fusion between phagosomes and lysosomes, thereby preventing the degradation of tumor antigens." (PMID 29462947, 2018). "In contrast, promoted tumor cell adhesion and invasion in a murine model have been reported to be associated with lipopolysaccharide (LPS) ligation to TLR444 and increased tumor progression and metastasis have been correlated with the silencing of TLR4 in a murine model of breast cancer." (PMID 30774831, 2018). "However, long-term activation of TLR4 cell signaling pathway in prostate epithelial cells may promote tumor cell activation, proliferation, survival, and tumor transformation." (PMID 29928275, 2018). "We concluded that combined modulation of Wnt/Dkk-3/claudin-5 and TLR-4 pathways, simultaneously targeting apoptosis and survival signaling defects, might shift the balance from tumor growth stasis to cytotoxic therapeutic responses, flowing in greater therapeutic benefits." (PMID 30680070, 2018). "In addition, HMGB1 binding of TLR2 and TLR4 plays an important role in tumor metastasis." (PMID 29636841, 2018). "Consequently, targeting TLR4/MyD88 signaling may be an attractive therapeutic strategy to hinder tumor progression." (PMID 28662055, 2017). "To clarify the detailed mechanism of anti-tumor immunomodulatory effects of APS and to verify whether APS activates TLR4 signaling pathway through MyD88-dependent pathway, we used C57BL/6J (MyD88+/+) and MyD88-deficient (MyD88−/−) tumor-bearing mice in this study." (PMID 28303957, 2017). "Studies have shown that the number of tumor-infiltrating T cells was positive correlated with secretion of HMGB1 by cancer cells, specialists speculated that the underlying mechanism may be related to activation of TLR4 by HMGB1 in tumor microenvironment." (PMID 29029545, 2017). "Except for immune cells, endothelial and various cancer cells also express TLR4, and chronic stimulation of TLR4 could promote tumor initiation, growth, and tumor immune escape and induce chemoresistance through pro-inflammatory responses and antiapoptotic signals." (PMID 28484456, 2017). "DAMPs and PAMPs from infection-related inflammatory, tumor-associated inflammatory, or antitumor therapy-induced inflammatory could upregulate the TLR4 expression and activate TLR4 signaling in tumor cells and contribute tumor pathogenesis and progression in a direct or indirect way." (PMID 28484456, 2017). "In addition, elevation of circulating TNFα and IL-6 in LLC tumor-bearing mice is dependent on TLR4." (PMID 28536426, 2017). "However, whether the immunomodulatory and anti-tumor effects of APS is mediated through TLR4 signaling pathway is still unclear." (PMID 28303957, 2017).